LGALS3 (galectin 3)
Diseases named in the same sentence as LGALS3 in open-access papers (continued):
Sharing a sentence is not in itself a finding about the gene and the disease.
melanoma (continued). "Utilizing shRNA to downregulate LAMP1 in B16F10 mouse melanoma cells can attenuate the induction of matrix metalloproteinase (MMP9) expression by the p38 MAPK signaling pathway activated by galectin-3 and polyN-acetyllactosamine (polyLacNAc)." (PMID 39669571, 2024). "In fact, galectin-3 expression is generally reduced in progressing melanoma cells, and in the context of targeted therapy, it was reported to induce sensitivity of melanoma cells to treatment." (PMID 38730718, 2024). "Galectin-3 has previously been reported to increase secretion of MMP-1 and −9 in melanoma cells by binding to lysosome-associated membrane protein-1 (LAMP1)." (PMID 37055381, 2023). "An early study showing that galectin-3 interaction with integrin-β3 increases melanoma cell adhesion and metastasis is in keeping with this possibility." (PMID 37612278, 2023). "Pre-incubation of melanoma cells with a truncated form of galectin-3 or by feeding the mice with a galectin-3 inhibitor (modified citrus pectin) in drinking water was shown to also reduce melanoma metastasis." (PMID 36291660, 2022). "It was found that the introduction of galectin-3 to A375, Mel270, and 92.1 cells caused a time-dependent increase in AKT phosphorylation of all three melanoma cells with peak AKT activation at 1–2 h." (PMID 36291660, 2022). "Galectin-3 is a galactoside-binding protein and is commonly overexpressed by many types of cancers including melanoma." (PMID 36291660, 2022). "This provides further support to the interaction of galectin-3 with the MCAM on the activation of downstream MCAM signalling in melanoma cells." (PMID 36291660, 2022). "Overall, galectin-3 is identified in this study as a natural ligand of the MCAM in melanoma cells, and their interaction induces MCAM clustering and subsequent AKT activation." (PMID 36291660, 2022). "As MCAM dimerization is known to occur in the activation of MCAM in melanoma, we then investigate the influence of exogenous introduction of galectin-3 on MCAM dimerization." (PMID 36291660, 2022). "In the present study, the interaction between galectin-3 and the MCAM in melanoma cells was seen to be mediated largely via O-linked carbohydrates on the MCAM." (PMID 36291660, 2022). "Together, these results indicate that the galectin-3–MCAM interaction promotes melanoma cell proliferation, adhesion, migration, and invasion." (PMID 36291660, 2022). "Increased expression of CSPG4 (chondroitin sulfate proteoglycan 4) and of PD-L1 in human melanoma cells are also dependent on galectin-3." (PMID 36361933, 2022). "VGVAPG also increased cells attachment and the expression of major adhesion molecules CD44, ICAM-1 and NCAM on melanoma cells through galectin-3 and integrin αvβ3 receptors." (PMID 35008401, 2022). "The proteins related to the survival of melanoma cells mainly include Galectin-3, Survivin, Dickkopf (DKK), Bcl-2, and so on." (PMID 36338621, 2022). "In cutaneous melanocytic lesions, melanoma and metastases more often displayed nuclear and cytoplasmic Galectin-3 than naevi." (PMID 34503258, 2021). "LGALS3 plays a significant role in the progression and metastasis of colon cancer, acute myeloid leukemia, melanoma, and pituitary tumors." (PMID 33712023, 2021). "In the lung, galectin-3 facilitates melanoma metastatic colonies by affecting tumor-cell adhesion and the innate immune response against melanoma by increasing serum IL-17 levels." (PMID 33138017, 2020). "Galectin-3 promotes cell adhesion, progression and metastasis in melanoma, and its expression is higher in abnormal melanocytes, in contrast to benign, banal melanocytes." (PMID 33150039, 2020). "Herein, we showed that galectin-3 (Gal-3), a β-galactoside binding lectin which is often lost along melanoma progression, is a negative regulator of autophagy in melanoma cells." (PMID 29581864, 2018).
melanoma (continued). "Excitingly, one of these trials showed that the combination of pembrolizumab with the galectin-3 inhibitor GR-MD-02 gave promising early results in the treatment of patients with advanced melanomas in a phase Ib clinical trial." (PMID 29389859, 2018). "We conclude that the induction of CD4+CD25hiFoxP3+ T cells and the expression of IDO and galectin-3 by melanoma cells are undesirable for a good expansion of tumor-reactive T cells in a MLTC." (PMID 28401257, 2017). "Human melanoma cell line LB33-MEL secretes galectin-3, which is found both in the supernatant and bound to the cell surface." (PMID 28986561, 2017). "It has been proposed that galectin-3 expression in melanoma cells is necessary for their ability to form tube-like structures on collagen type I matrix." (PMID 27242966, 2016). "In contrast, More SK, 2015 found that C57/BL6 Lgals3−/− mice showed similar extent of B16F10 melanoma metastatic colonies in the lung as the Lgals3+/+ mice." (PMID 27526676, 2016). "Other inflammatory markers, as CRP and galectin-3, were prior correlated in melanoma with an increase in LDH and circulatory markers such as S100 and MIA." (PMID 26504364, 2015). "The concentration of galectin-3 is elevated by up to 30-fold in the circulation of cancer patients including those with colon, breast, pancreatic, melanoma, lung, head and neck, and ovarian cancer and non-Hodgkin's lymphoma." (PMID 26160844, 2015). "Pre-treatment of MUC1-expressing human melanoma ACA19+ cells with galectin-3 before application of the cells to HUVEC monolayers resulted in a ∼50% increase of cell adhesion in comparison to the BSA-treated control cells." (PMID 26160844, 2015). "As far as we know, it is shown here for the first time that galectin-3 expression recovery in a melanoma cell increases VEGF secretion." (PMID 24421272, 2014). "Galectin-3 expression was reconstituted in a melanoma cell line that lacks this lectin and both expressing galectin-3 or galectin-3 null parental cells were inoculated in galectin-3 KO or WT mice." (PMID 24982845, 2014). "Galectin-3 contributes to melanoma growth and metastasis via regulation of NFAT1 and autotaxin, and Galectin-3 regulates p21 stability in human prostate cancer cells." (PMID 25260879, 2014). "Our results demonstrated that melanoma cells expressing galectin-3 (Tm1G3) secreted larger amounts of VEGF in vitro than Tm1N3 cells, even without any specific stimulus." (PMID 24421272, 2014). "Here we have used a metabolomics approach to identify conditions in which de novo expression of an established tumor marker, galectin-3, would confer a potential selective advantage for melanoma growth and survival." (PMID 25221735, 2014). "The β1-6-branched N-glycans extended with poly-N-acetyllactosamine chains facilitate lung-specific metastasis of melanoma cells via galectin-3." (PMID 22544341, 2013). "It has been shown that LGALS3 is regulated by the microphthalmia-associated transcription factor (MITF), which has a pivotal role in melanocyte development and melanoma." (PMID 22216283, 2011). "Sera of melanoma and colon adenocarcinoma patients were reported to contain more galectin-3 than sera of healthy volunteers." (PMID 24212939, 2011). "The concentration of free circulating galectin-3 is markedly increased in the sera of patients with breast, colorectal, lung, head and neck cancers and melanoma." (PMID 20565834, 2010). "On the other hand, there are antigens such as galectin-3 that were found by proteome serology so far only for melanoma, and others only for other cancers." (PMID 19381273, 2009). "Notably, proteins associated with cell adhesion and mobility, such as VIM, CTTN, and LGALS3, are more abundant in melanoma cells." (PMID 40775377, 2025). "Galectin-3 is a β-galactoside-binding protein and is overexpressed in various types of epithelial cancer including colorectal, breast, lung, prostate, pancreatic, head and neck cancer and melanoma." (PMID 37055381, 2023).
melanoma (continued). "Galectin-3 (Gal-3) serves as a pivotal molecule in the intricate landscape of oncology, with expression patterns spanning a multitude of malignancies, including gastrointestinal, cardiovascular, urinary, respiratory, breast, melanoma, and thyroid systems." (PMID 37892182, 2023). "In this study, galectin-3 was shown to be naturally associated with MCAM in melanoma cells, and their interaction promotes melanoma cell proliferation, adhesion, migration, and invasion, all of which are important steps in melanoma progression." (PMID 36291660, 2022). "Suppression of the cellular expression of poly-N-acetyl-lactosamine, a disaccharide that is recognized by galectin-3 and occurs in various N-linked carbohydrate structures of cell membrane glycoproteins including MCAM, showed to substantially reduce melanoma metastasis in mice." (PMID 36291660, 2022). "Moreover, we observed that under the influence of melanoma, HaCaT keratinocytes secrete higher amounts of galectin 3, which is involved in cell migration." (PMID 36123693, 2022). "Targeting the galectin-3–MCAM interaction may potentially be a useful therapeutic strategy for melanoma treatment." (PMID 36291660, 2022). "It is possible that galectin-3–MCAM interaction-mediated effects on melanoma cell proliferation, adhesion, and invasion may also involve the activation of other downstream signalling pathways in addition to AKT pathways." (PMID 36291660, 2022). "It is therefore not surprising that binding of galectin-3 to the highly glycosylated MCAM in melanoma cells also causes MCAM clustering on the cell surface." (PMID 36291660, 2022). "Targeting the galectin-3–MCAM interaction therefore may potentially be a useful therapeutic strategy for melanoma treatment." (PMID 36291660, 2022). "Thus, galectin-3 is a natural binding ligand of MCAM in melanoma, and their interaction activates MCAM and promotes MCAM-mediated melanoma progression." (PMID 36291660, 2022). "The target predictions indicate that TPPS may interact with four melanoma targets: telomerase reverse transcriptase, C-X-C chemokine receptor type 4, histone deacetylase 1, and galectin-3." (PMID 36365208, 2022). "However, in some malignant diseases, in particular melanoma and glioblastoma, the presence of galectin-3 is beneficial for patients." (PMID 36140182, 2022). "Galectin-3 is another NKp30 ligand that is expressed on melanoma cells." (PMID 33802954, 2021). "Galectin-3 expression is positively correlated with the metastatic potential of human melanoma cell lines; it plays an important role in cell–matrix adhesion during melanoma progression." (PMID 34885166, 2021). "Galectin-3 also increases vascularization of prostate tumors and melanomas." (PMID 34900729, 2021). "Galectin-3 and enolase two overexpression were detected in the transfected metastatic cell line, and we assume that both play an important role in promoting the aggressive phenotype of melanoma cells." (PMID 34257527, 2021). "Linked by a network of overlapping functions in melanoma progression, melanoma cell adhesion molecule (MCAM), galectin-3 (Gal-3), chondroitin sulfate proteoglycan 4 (CSPG4), matrix metalloproteinase 2 (MMP-2), and paired box 3 (PAX-3) potentially act as biomarkers and targets in melanoma metastasis." (PMID 33490091, 2020). "Moreover, we demonstrate that tumor-relevant genes, such as FosB, WEE1, PVR, MAP1LC3B, and LGALS3, are deregulated in melanoma by direct regulation via c-Jun5." (PMID 31378787, 2019). "Furthermore, in melanoma models, the interaction between poly-LacNAcs and galectin-3 (Gal-3) regulates metastasis." (PMID 31126011, 2019). "Until November 2017, two clinical trials have been reported using the galectin-3 inhibitor DG-MD-02 along with ipilimumab (anti-CTLA-4) or pembrolizumab (anti-PD-1) to treat patients diagnosed with melanomas, non-small cell lung cancers, and squamous cell head and neck cancers." (PMID 29389859, 2018).
melanoma (continued). "However, in melanoma cells, IFN-γ stimulation causes galectin-3 downregulation followed by cell growth inhibition." (PMID 26934444, 2016). "In addition, it has been reported that extracellular galectin-3 induces MMP-9 expression via p38 MAPK pathway in melanoma cells." (PMID 27242966, 2016). "Intravenous injection of such heparin derivatives (with cancer cells pre-treated with galectin-3 followed by 3 subcutaneous injections of the derivatives) abolished the circulating galectin-3-mediated increase in lung metastasis of human melanoma and colon cancer cells in nude mice." (PMID 26160844, 2015). "In order to access the impact of galectin-3 expression in melanoma engraftment and tumor growth, Tm1 cells were successfully transfected with a plasmid containing human cDNA for galectin-3 or the empty vector, generating stable clones, designated as Tm1G3 and Tm1N3, respectively." (PMID 24421272, 2014). "On a biological perspective, galectin-3 may interfere in the metabolism of melanoma cells specifically under such conditions." (PMID 25221735, 2014). "In this regard, exogenous or tumor-derived galectin-3 was shown to increase melanoma and colon cancer cells homotypic and heterotypic adhesions by interaction with oncofetal Thomsen–Friedenreich carbohydrate on the cancer-associated transmembrane mucin protein (MUC1)." (PMID 24982845, 2014). "Galectin-3 is expressed in the nucleus, cytoplasm, and plasma membrane of melanoma cells." (PMID 24069584, 2013). "From these reviews and others we have identified five melanoma biomarkers consistently associated with melanoma progression – melanoma cell adhesion molecule (MCAM), galectin-3 (Gal-3), matrix metalloproteinase-2 (MMP-2), chondroitin sulfate proteoglycan 4 (CSPG4), and paired box 3 (PAX3)." (PMID 24069584, 2013). "Galectin-3 binds to N-linked oligosaccharides within the D3 domain of the CSPG4 core protein and to oligosaccharides on β1 to form a complex that can be immunoprecipitated from human melanoma cell surfaces." (PMID 24069584, 2013). "The expression of galectin-3 was higher in thin primary melanoma lesions than in benign pigmented skin lesions or metastases and seemed to correlate inversely with the aggressiveness as estimated by the Breslow index, which is recognized as the main prognostic factor in melanoma." (PMID 23658855, 2010). "The recent study of this group clearly demonstrates that galectin-3 could be of prognostic value in melanoma patients; more precisely, this protein has a strong independent prognostic signification with a cut-off value of 10 ng/mL." (PMID 23658855, 2010). "Only one of the antigens reported herein, galectin-3, had already been reported for melanoma." (PMID 19381273, 2009). "It will be interesting in future research to determine whether the strength of galectin-3 interaction with the melanoma-derived MCAM is higher than its interaction with the recombinant form of MCAM using biophysical approaches such as isothermal titration calorimetry and surface plasmon resonance." (PMID 36291660, 2022). "Galectin-3 concentration was shown to be significantly higher in the group of patients with melanoma compared with healthy volunteers, and galectin-3 concentration significantly correlated with both serum lactate dehydrogenase and C-reactive protein in the melanoma group." (PMID 23658855, 2010). "In melanoma, CTLA-4 and vascular endothelial growth factor A blockade elicited a humoral response to Galectin-3 that correlated with improved patient outcomes." (PMID 41477833, 2026). "When comparing monocytes to melanoma cells, proteins such as VIM, LMNA, CALU, LGALS3, CTTN, and CORO1A are strongly and confidently differentially expressed." (PMID 40775377, 2025). "In melanoma, the interaction between MCAM and Galectin-3 promotes tumor progression by activating the AKT signaling pathway." (PMID 40221534, 2025).
melanoma (continued). "STRING-based PPI networks centered on TGF-β revealed high-confidence connectivity with fibrotic, angiogenic, and immunomodulatory cytokines such as VEGF, Galectin-3, and CXCL1, which the Dox-treated melanoma cells also enriched in their released EVs." (PMID 40943445, 2025). "In the B16F10 melanoma tumor tissue and in the normal melanocyte (M0) and malignant A375 cells, the effects of exogenous ARSB and of ARSB and galectin-3 knockdown were evaluated." (PMID 38892038, 2024). "In the melanoma tissue of the C57BL/6J mice, treatment with exogenous ARSB reduced the free galectin-3 (p < 0.0001)." (PMID 38892038, 2024). "In the subcutaneous mouse melanoma tissue, HDAC3 activity increased following exogenous ARSB (p < 0.0001), in contrast to the decline in free galectin-3." (PMID 38892038, 2024). "The epigenetic mechanism in the melanoma cells affecting PD-L1 expression resembles the previously observed mechanisms by which ARSB and chondroitin 4-sulfation affect galectin-3 and AP-1, as shown by transcriptional effects on HIF-1α, Wnt9a, and versican." (PMID 38892038, 2024). "Furthermore, galactose polymers can potentially be used to target galectin-3, which is overexpressed in some cell lines, such as the melanoma cell line A375, as was the case light responsive galactose-based glycopolymer (Entry 26), which showed selective cytotoxicity in human melanoma cells." (PMID 36986774, 2023). "VGVAPG increased the migration of melanoma cells and the generation of elastin-derived peptides, enhancing the expression of elastin-degrading MMP-2 and MMP-3 through binding to galectin-3 and EBP receptors." (PMID 35008401, 2022). "Galectin-3 shows high serum levels in advanced melanoma patients and is also regarded as an important biomarker for prognosis in stage III and IV melanoma patients." (PMID 36338621, 2022). "On the other hand EGFR, galectin-3 and OPN potentially influence the extracellular signal-regulated RAF/MEK/ERK pathway [59, –, 62], and both pathways are fundamental in melanoma tumorigenesis." (PMID 34257527, 2021). "Our results revealed for the first time that silencing the OPN gene influences proliferation and invasion of melanoma cells by effecting EGFR, tenascin C, survivin, galectin-3 and enolase 2 expression." (PMID 34257527, 2021). "The cytotoxic effect of Cu-2 against melanoma cells was evaluated using a model of vertical growth melanoma (TM1), in which galectin-3 (GAL3) expression is lost during tumor progression." (PMID 33614708, 2020). "Thus, when Borges and collaborators investigated the effect of copper complexes in melanoma cells, they demonstrated that the metal treatment increased the levels of intracellular reactive oxygen species (ROS), which was accompanied by p38 activation in galectin-3-expressing melanoma cells." (PMID 27242966, 2016). "On the other hand, a study using B16F10 melanoma cell and LLC lung cancer cells in an allograft model and found an increased primary solid tumor growth in C57/BL6 Lgals3−/− mice compared with Lgals3+/+ mice in both B16 and LLC tumors." (PMID 27526676, 2016). "Again, in a metastatic murine melanoma cell line, B16F10, knocking down of galectin-3 reduced cell migration and invasion as well as MMP-1 levels." (PMID 27242966, 2016). "In this study, they showed that, compared with wild-type (WT) mice, galectin-3 KO mice presented a markedly reduced number and size of metastatic colonies in an experimental model of lung B16F1 murine melanoma metastasis." (PMID 24982845, 2014). "Of the identified antigens, galectin-3 and HSP60 most often induce antibody responses in melanoma patients followed by calumenin and enolase I. For HSP60 and calumenin seroreactivity was also detected in healthy donors tested." (PMID 19381273, 2009).